PPARA (peroxisome proliferator activated receptor alpha)
Diseases named in the same sentence as PPARA in open-access papers (continued):
Sharing a sentence is not in itself a finding about the gene and the disease.
mesothelioma (1 paper, 2022). A usually malignant and aggressive neoplasm of the mesothelium which is often associated with exposure to asbestos. "Using two intrapleural models, we identified PPARα and PPARγ as potential regulators of an invasion-associated gene expression signature in mesothelioma." (PMID 34984327, 2022). "Because we identified PPARα and PPARγ as potential regulators of a transcriptional program underlying the invasive and proliferative behavior of mesothelioma in the pleural space, we hypothesized that antagonizing these regulators would alter tumor cell invasion and proliferation." (PMID 34984327, 2022). "Altogether, our data invalidate dual antagonism of PPARα and γ to reduce the growth or invasion of mesothelioma." (PMID 34984327, 2022). "We observed a significant increase in proliferation, but only in the HAP1 parental cell line, not in the PPARA/PPARG KO cells (p. value <0.0001), suggesting that arachidonic acid induced increased mesothelioma cell proliferation in a PPARα- and PPARγ-dependent manner." (PMID 34984327, 2022). "The identification of GW6471 as the first potent, dual PPARα/γ antagonist provided the opportunity to test the hypothesis that concurrent antagonism of both PPARα and γ could be an effective mesothelioma treatment." (PMID 34984327, 2022). "We conclude that dual PPARα/γ antagonism alone is not a viable treatment modality for mesothelioma." (PMID 34984327, 2022). "Although our results show that dual targeting of PPARα/γ is not an effective treatment strategy for mesothelioma, we note that genetic deletion of PPARγ may reduce invasion and proliferation of tumors in vitro." (PMID 34984327, 2022). "However, administration of GW6471 at doses that provided sustained plasma exposure levels sufficient for inhibition of PPARα/γ transcriptional activity did not result in significant anti-mesothelioma activity in mice." (PMID 34984327, 2022). "Together, these findings show that therapeutic antagonism of PPARα and γ using GW6471 has no impact on mesothelioma invasion and proliferation in vivo." (PMID 34984327, 2022).
migraine (1 paper, 2025). "The authors suggest that PPARα and PPARβ/δ serve in a protective role during migraine and that the reduction of PPARγ accelerates migraine." (PMID 40630421, 2025). "PPARα and PPARβ/δ appear to be involved in migraine resolution through their anti-inflammatory activities and PPARγ is involved in migraine onset." (PMID 40630421, 2025).
Nasal polyps (1 paper, 2005). "Nasal polyps exhibited lower mRNA expression levels of PPARα and PPARγ than normal nasal mucosa and these levels were, for PPARγ, further reduced following four weeks of treatment with local steroids." (PMID 16271155, 2005). "The RT-PCR analysis of total RNA extracted from nasal biopsies and nasal polyps demonstrated the presence of PPARα, PPARβδ, PPARγ and β-actin in all samples." (PMID 16271155, 2005). "Nasal polyps exhibited lower levels of PPARα and PPARγ than normal nasal mucosa and these levels were, for PPARγ, further reduced following steroid treatment." (PMID 16271155, 2005).
nephrocalcinosis (1 paper, 2018). Nephrocalcinosis is a disorder that occurs when too much calcium is deposited in the kidneys. "Intrarenal mRNA expression profiling revealed that peroxisome proliferator-activated receptor gamma coactivator 1 alpha, peroxisome proliferator-activated receptor alpha, and peroxisomal acyl-coenzyme A oxidase 1 were reduced in mice with nephrocalcinosis (oxalate only, red bars)." (PMID 29651290, 2018).
neuronal ceroid lipofuscinosis (1 paper, 2023). "It increases the lifespan of Cln2(−/−) mice, an animal model of late-infantile neuronal ceroid lipofuscinosis, via PPARα." (PMID 38132111, 2023).
parotid tumors (1 paper, 2021). "Therefore, all three PPAR family members (PPARα, -β and -γ) were characterized in parotid tumors." (PMID 34360635, 2021).
periapical granuloma (1 paper, 2021). Chronic nonsuppurative inflammation of periapical tissue resulting from irritation following pulp disease or endodontic treatment. "Nuclear receptor transcription factors (RXR and VDR), posttranscriptional gene silencing, and PPARA pathways were the most abundant pathways related to periapical granuloma." (PMID 34539639, 2021).
relapsing-remitting MS (1 paper, 2020). "We demonstrate that monocytes of relapsing-remitting MS patients display a marked decrease in PPARγ expression, while the expression of PPARα and LXRα/β is not altered." (PMID 33297574, 2020).
Sandhoff disease (1 paper, 2024). A lysosomal disorder from the GM2 gangliosidosis family, caused by biallelic pathogenic variants in the HEXB gene, characterized by GM2 ganglioside accumulation in the nervous system and progressive central nervous system degeneration. "In summary, our study demonstrates that oral CA treatment attenuates glial inflammation, reduces glycoconjugate accumulation, decreases neuronal apoptosis, improves gait & locomotor activities, and increases survival in a mouse model of Sandhoff disease through PPARα." (PMID 38532783, 2024).
Sjögren-Larsson Syndrome (1 paper, 2021). "Notably, PPARα induces FALDH expression and the PPARα agonist Bezafibrate has been suggested as an agent for treating Sjögren-Larsson Syndrome patients with partially inactivated FALDH." (PMID 34237064, 2021).
Splenomegaly (1 paper, 2022). Abnormal increased size of the spleen. "Non-lethal doses of LPS induced strong splenomegaly that was impaired by WIN55212-2 through mechanisms depending on autophagy, CB1 and PPARα." (PMID 34548620, 2022).
staphylococcal infection (1 paper, 2024). An infection caused by Staphylococcus. "The staphylococcal infection phenotype shows the robust impact of PPARα on the innate immune response, even in a resistant mouse strain." (PMID 38601738, 2024).
temporal lobe epilepsy (1 paper, 2025). A localization-related (focal) form of epilepsy characterized by recurrent seizures that arise from foci within the temporal lobe, most commonly from its mesial aspect. "Our study provides the first comprehensive evidence that the PPARα agonist fenofibrate exerts a complex, region-specific modulation of neuroinflammation and synaptic plasticity during the latent phase of the lithium-pilocarpine model of temporal lobe epilepsy." (PMID 41009625, 2025).
testicular tumors (1 paper, 2015). "The test chemical belongs to a class of compounds known as peroxisome proliferators (PPARα agonists) which are known to produce liver, pancreatic, and testicular tumors in rats and liver tumors in mice." (PMID 28962433, 2015).
thymoma (1 paper, 2022). A neoplasm arising from the epithelial cells of the thymus.
tubular adenoma (1 paper, 2009). A usually polypoid neoplasm arising from the glandular epithelium. "The decrease of PPARα in tumors confirms the observation of other authors that a significant decrease in its expression is found in human tubular adenomas compared to normal human colonic epithelial cells." (PMID 19841681, 2009).
tularemia (1 paper, 2010). Tularemia is an infection caused by the bacterium Francisella tularensis. "Future studies aimed at examining the effect of Ft LVS or type A strains on the hepatic and pulmonary pathology following cell-specific deletion of PPARα or γ from immune cells are needed to further dissect the role of PPARs in the pathogenesis and prevention of tularemia." (PMID 20082697, 2010).
uremia (1 paper, 2021). A clinical syndrome associated with the retention of renal waste products or uremic toxins in the blood. "Production of this protein is suppressed by peroxisome proliferator-activated receptors (PPARα), which is downregulated during uremia in ESKD patients and during insulin-resistant states." (PMID 34822432, 2021).
vascular dementia (1 paper, 2022). A degenerative vascular disorder affecting the brain. "SMYZG activates and regulates four main signaling pathways relevant to vascular dementia including the AMPK/PPARα/PGC-1α/UCP2, Nrf2/HO-1, HIF-1/VEGF/Notch, and VEGF/Flk-1/p8 MAPK pathways." (PMID 36507350, 2022).
cancer (768 papers, 2005 to 2026). A tumor composed of atypical neoplastic, often pleomorphic cells that invade other tissues. "Target mapping implicated clinically relevant proteins such as carbonic anhydrase 2 (CA2), PARP1, and PPARA, associated with metabolic disorders, neurodegeneration, and cancer." (PMID 42221505, 2026). "Mechanistically, deficient PPARα-mediated lipophagy leads to the accumulation of ether-lipids within cancer cells, which in turn promotes cell mobility via calcium-dependent, TRPV2 channel-mediated cytoskeletal rearrangement." (PMID 40936093, 2025). "Different PPARs have significant effects on cancer: PPARα is implicated in promoting proliferation, whereas PPARγ exhibits the opposite effect." (PMID 38835342, 2024). "Activation of PPARα has been associated with anti-inflammatory effects and inhibition of tumor growth in certain types of cancer." (PMID 37645246, 2023). "In conclusion, although PPARα and PPARγ seem to decrease tumor angiogenesis, caution should be taken regarding the therapeutical use of any PPAR agonist in the setting of susceptibility to cancer." (PMID 35954274, 2022). "In a word, although PPARα is associated with the progress of pan-cancer according to omics analysis, the role of PPARα in cancer remains uncertain." (PMID 36589809, 2022). "Consistent with this study, mice expressing a human PPARα were less susceptible to develop cancer with agonist administration." (PMID 23024649, 2012). "While PPARγ activation in NHU cell cultures inducesdifferentiation, someselective PPARγ and most dual-acting PPARα+γ agonists causebladder cancer in rats." (PMID 19197366, 2008). "In recentyears, an inflammation-associated model of cancers has been given attention.PPARα exerts anti-inflammation effects by repressing nuclear factor kappa B(NFκB), whichinhibits inflammation signaling and subsequent cancer." (PMID 18769559, 2008). "Althoughactivation of PPARα in either endothelial or tumor cells hasbeen proven to be beneficial in inhibiting cancer growth, it has also beenshown that loss of host-derived PPARα can be advantageous as it preventstumor growth and development." (PMID 18725983, 2008). "Additionally, CD133 has been associated with upregulation of Peroxisome proliferator-activated receptor alpha in cancer stem cells, which is essential for retinal lipid metabolism." (PMID 38956727, 2024). "Reduced FAO and downregulation of PPARA the master regulator of lipid catabolism have also been linked to susceptibility to ferroptosis in other cancer models while increased uptake of PUFA via CD36 has been shown to trigger ferroptotic cell death/susceptibility in T cells." (PMID 37059720, 2023). "The symmetrical division ability of stem cells enhanced tissue developmental plasticity and liver regeneration capacity, but over-proliferation might cause cancer, and PPARα activation could effectively resist cancer risk." (PMID 36168631, 2022). "Enriched pathways for upregulated miRNAs included: “Chemical carcinogenesis–receptor activation” (p-value = 0.018) associated with ESR1, FGF18, JAG1, KPNA6, PPARA genes; the pathway “Proteoglycans in cancer” (p-value = 0.089) associated with genes ESR1, FRS2, HIF1A, PDCD4." (PMID 36359024, 2022). "Strikingly, arachidonic acid is a known PPARα- and γ-activating ligand, which is released after injury or irritation as an inflammatory mediator, and has been previously linked to cancer progression." (PMID 34984327, 2022). "Additionally, the PPARα agonist, fenofibrate, caused inhibitory effects in different cancer cell lines and animal tumor models, including hepatocarcinogenesis." (PMID 35280774, 2022). "However, some studies implicated PPARα in the promotion of cancer while others presented evidence for an antitumorigenic role." (PMID 31779269, 2019).
cancer (continued). "Given that PPAR ligands are currently used in medicine as hypolipidemic drugs with excellent tolerance and limited toxicity, PPARα activation might offer a novel and potentially low-toxic approach for the treatment of tumor-associated angiogenesis and cancer." (PMID 18725983, 2008). "Chronic pharmacological activation of PPARα is invariably associated with cancer in rats and mice." (PMID 19197366, 2008). "The particularity of PPARα to be expressed in peripheral tissues makes it crucial in relevant metabolic pathways implicated in the physiopathology of prevalent diseases, such as diabetes, hypertension, atherosclerosis, inflammation, cancer, or neurodegeneration." (PMID 32536865, 2020). "Thus, digoxin may have a novel ability to suppress cancer invasiveness and progression via pathways associated with PPARα." (PMID 31719612, 2019). "Our results demonstrate that cancer‐derived CCL2 acts as a signaling molecule that regulates lipid metabolism in adipose tissues through the CCL2/CCR2/PPARα pathway." (PMID 41160815, 2026). "Activation of HIF‐1α induced by FA influx increases CCL2 expression in cancer cells, which subsequently leads to lipolysis in nearby adipose tissue by activating peroxisome proliferator‐activated receptor alpha (PPARα) signaling." (PMID 41160815, 2026). "PPARα promotes cancer growth and survival in multiple ways, such as increasing ketogenesis, fatty acid transportation, and synthesis." (PMID 39859448, 2025). "The regulation of PPARα in cancer progression is controversial, as it can act either as a tumor inducer or suppressor in specific cancer cell types." (PMID 40936093, 2025). "PPARα was also shown to suppress cancer cell growth through NF-kB and IkBα signaling pathway in vitro." (PMID 40936093, 2025). "In fast-running racehorse breeds, the SNP with the highest Fst ranking was found to involve NDUFB7, and this gene is directly regulated by PPARA in cancer models." (PMID 40723531, 2025). "Most studies indicate that PPARα regulates lipid catabolism-related genes and mediates its downstream signal pathway, thereby promoting cancer progression." (PMID 40936093, 2025). "Elevated PPARA expression has been demonstrated in several cancers, such as ampullary cancer and stomach adenocarcinomas." (PMID 41148824, 2025). "It plays a role in cancer treatment by regulating related lipid metabolism pathways, such as the PPARα/RXR pathway." (PMID 40351413, 2025). "Mechanistically, cancer-associated adipocytes (CAAs) secrete IL-6 and release free fatty acids (FFAs), which serve as metabolic sensors to activate ANGPTL4 via STAT3 and PPARα signaling pathways in TNBC cells." (PMID 40616161, 2025). "PPARα is involved in several types of cancer through the activation of NF-kB and the regulation of fatty acid oxidation." (PMID 39660001, 2024). "TPST-1120 is a novel investigational agent designed to therapeutically target cancer cells and enhance anticancer immunity by inhibiting the fatty acid ligand-activated transcription factor PPARα." (PMID 38551394, 2024). "As an argument, they cited that using one of the experimental ligands initially significantly reduces, by decreasing the PPARα activity, the rate of cancer cell proliferation." (PMID 39062500, 2024). "Peroxisome proliferator-activated receptor (PPAR) is a nuclear TF induced by ligands that plays a role in metabolism and cancer, including PPARα, PPARβ/δ and PPARγ." (PMID 38561775, 2024). "Because of its critical roles in metabolic regulation and immune function, PPARα has emerged as a target of interest for cancer therapy." (PMID 38551394, 2024). "PPARα is upregulated in various cancers, and modulation of PPARα activity by agonists or antagonists influences both pro- and antitumoral effects." (PMID 39519311, 2024).